MMP9 (matrix metallopeptidase 9)
Diseases named in the same sentence as MMP9 in open-access papers (continued):
Sharing a sentence is not in itself a finding about the gene and the disease.
lung carcinoma (continued). "Our results showed that epigenetic regulation of CD44v6, Nm23-H1, MMP-2, and MMP-9 might be involved in the pathogenesis and metastasis of lung cancer." (PMID 34400947, 2021). "Furthermore, silencing FGFRL1 with siRNA promoted the migration and invasion of lung cancer cells and up‐regulated expression levels of N‐cadherin, MMP‐9 and MMP‐1, whereas E‐cadherin expression was down‐regulated." (PMID 32396269, 2020). "In addition, honokiol‐inhibited MMP‐9 expression was rescued in HDAC6‐overexpressed lung cancer cells." (PMID 32180962, 2020). "As an overexpression of the lncRNA, MVIH is associated with tumor angiogenesis and MVIH expression is upregulated in lung cancer, further influencing MMP2 and MMP9, it may affect lung cancer tumor angiogenesis." (PMID 32992718, 2020). "One study reported that 3T3-L1 adipocyte-derived exosomes could enhance the expression of MMP3 in cancer cells that alleviated lung cancer metastasis by activating MMP9." (PMID 33374978, 2020). "The decrease in MMP-9 when two drugs were combined might contribute to the decreased migration ability of lung cancer cells in our experiment." (PMID 32792943, 2020). "Taken together, the MMP family (including MMP9) may be a bridge connecting the external physical electric field stimulation and the response of lung cancer cells." (PMID 32210363, 2020). "Interestingly, we observed a profound induction of MMP9 mRNA expression in lung cancer cells in response to co-culture with MSCs." (PMID 33119681, 2020). "Thus, among the MMP cohort analyzed, MMP9 mRNA expression is selectively upregulated in lung cancer cells in the presence of MSCs." (PMID 33119681, 2020). "Ang II/ATR1 pathway activation has been shown to promote EMT in cancer cells, which is a hallmark of cancer aggressiveness, while chymase, a protease that converts Ang I to Ang II, increased the expression of MMP-9 in a dose dependent manner in two lung cancer cell lines (A549 and H520)." (PMID 32503281, 2020). "Moreover, we show that ABL expression and kinase activity are required for MSC-induced MMP9 secretion by lung cancer cells." (PMID 33119681, 2020). "Indeed, our results show that blocking the ERα/CCL2 axis by shCCL2 can reduce macrophage M2 polarization and MMP9 production, which will further lead to the change of invasion of lung cancer cells." (PMID 32356397, 2020). "Disruption of MMP‐9 protein associated with Hsp90 and following by MMP‐9 degradation leading to the repression of migration and invasion activity via honokiol might result from HDAC6 inhibition in lung cancer cells." (PMID 32180962, 2020). "Further, knockdown of RPS6 in SK-MES-1 and H1650 lung cancer cells reduced their invasive ability and decreased MMP9 and MMP2 expression, suggesting that high levels of RPS6 may promote lung cancer metastasis." (PMID 32862831, 2020). "Moreover, MMP-9 was identified to be involved in the invasiveness and metastasis of cervical cancer, as well as other malignant tumors including lung cancer, oseteosarcoma, renal cancer." (PMID 32342983, 2020). "The results demonstrated that the metastasis suppression in lung cancer cell by honokiol might be through epigenetic regulation of MMP‐9 expression via ubiquitin/proteasome degradation." (PMID 32180962, 2020). "Our data showed that increasing ERα via adding ERα‐cDNA in lung cancer A549 cells could increase the MMP9 mRNA expression in cocultured THP‐1 cells (left)." (PMID 32356397, 2020). "The upstream targets that promote the up-regulation of MMP-9 in irradiated lung cancer cells remain unclear." (PMID 32143669, 2020).
lung carcinoma (continued). "In the present study, MMP9 is a response signal molecule of lung cancer cells to dcEF stimulation, suggesting that MMP9 may also be involved in external physical stimulation feedback of lung cancer cells, such as dcEF." (PMID 32210363, 2020). "High expression of MMP‐9 is also identified in lung cancer patients with low 5‐year survival rate." (PMID 32180962, 2020). "HSP90 has been reported to promote invasion and activate MMP9 in lung cancer cells." (PMID 30867003, 2019). "Moreover, a meta-analysis on MMP9 serum concentration in lung cancer, including 26 studies, concluded that MMP9 overexpression correlated with advanced tumor stage and poor 5-year OS." (PMID 31191742, 2019). "Likewise, CoQ10 caused a decrease in O2− level in mitochondria, inhibited MMP2 and MMP9 activity, and reduced tumor volume and the number of metastasis in mouse lung carcinoma." (PMID 30984333, 2019). "Therefore, it is necessary to carefully observe changes in TIMP-1 levels in addition to MMP-2 and MMP-9 to analyze lung cancer migration in the microgravity environment." (PMID 31601869, 2019). "The present study is a case–control study aimed to demonstrate the effects of the association between the MMP9 -1562C/T (rs3918242) and MMP13 -77A/G (rs2252070) gene polymorphisms, alone or under interaction, and the risk of lung cancer in our Chinese Population." (PMID 30889876, 2019). "In lung cancer has been demonstrated the concomitant overexpression of PTTG1 or MMP9." (PMID 31572301, 2019). "Moreover, the object of carrying MMP9 CC and MMP13 GG genotypes along showed a significantly increased risk of lung cancer (p = 0.00, OR = 5.34, 95% CI = 2.46–11.60) compared with other genotypes." (PMID 30889876, 2019). "Moreover, Dex-IR significantly inhibited the invasiveness of lung cancer cells by modulating the suppression of MMP9 activity." (PMID 29617386, 2018). "Interestingly, Kim and colleagues found that tumour metastasis with high WSB-1 expression presented increased expression of MMP2 and MMP9 levels in patients with lung cancer." (PMID 29540773, 2018). "Similarly the decreased activity of MMP-9 was also found in the casticin-mediated inhibitory effect on the invasion of lung cancer stem-like cells." (PMID 30401729, 2018). "HGF may also play a role in governing MMP-9 expression levels, as HGF antagonists have demonstrated the ability to downregulate MMP-9 activity in lung cancer cells." (PMID 30314527, 2018). "The relevant expression of MMP-9 in lung tissue induces lung cancer." (PMID 28969037, 2017). "It has been reported that CCL5 could acts through PI3K/Akt, which in turn activates IKKα/β and NF-κB, and contributing to the migration of human lung cancer cells, and NF-κB activation could promote the expression of MMP9." (PMID 29088737, 2017). "Elevated expression of DLK1 was reported in neuroblastoma from patients with poor outcome and induction of DLK1 expression in lung cancer activated both notch-dependent signaling and upregulated matrix metalloproteinase MMP9, which increased cellular invasive potential." (PMID 28871274, 2017). "Therefore, before using A549 cells in a tumor xenograft model, we first examined the effects of isothiocyanates on TPA-induced MMP-9 activity in A549 lung cancer cells." (PMID 28969043, 2017). "In this study, we investigated the role of NMI in the regulation of cell proliferation, apoptosis, and migration in human lung cancers, and also explored its underlying molecular mechanisms involved in PI3K/AKT, Erk/p38, MMP9/β-cadherin, NF-κB/COX-2/PGE2, and PARP/Bcl-2/Caspase3 signaling pathways." (PMID 29025423, 2017). "Our results show that MMP9 is relatively high expressed in lung cancer tissues." (PMID 28148898, 2017). "In lung carcinoma cell line, inactivation of MMP9 can inhibit tumor invasion." (PMID 28148898, 2017). "Moreover, uPA and MMP9 expression by TAMs in breast and lung cancers correlated with increased angiogenesis and invasion, and poor patient survival." (PMID 27487154, 2016).
lung carcinoma (continued). "In addition, IL-17 promoted MMP2 and MMP9 secretion by A549 cells, which promoted the invasion and metastasis of lung cancer." (PMID 27872514, 2016). "TRIM29 upregulates MMP-9 to promote lung cancer cell invasion by activating ERK and JNK pathways." (PMID 27145374, 2016). "In bladder and lung carcinoma cells, it inhibits matrix metallopeptidase-9 (MMP-9) expression." (PMID 27877185, 2016). "Previous research also showed that SPAG9 might act as an important promoter of tumor invasion via the SPAG9/JNK/MMP9 pathway in lung cancer." (PMID 26790956, 2016). "Lung cancer cells, both primary and metastatic, can express MMP-9 constitutively, which may correlate with metastatic potential." (PMID 27375834, 2016). "Importantly, MMP9 inhibition decreased the TNF-α- and EGF-stimulated invasiveness of A549 cells, highlighting the importance of the S100A4/MMP9 axis in S100A4-driven invasion in lung cancer cells." (PMID 27127879, 2016). "Importantly, our study demonstrates that niclosamide dramatically inhibits the NF-κB/MMP9 signaling axis by suppressing S100A4 to block the invasive capacity of lung cancer cells." (PMID 27127879, 2016). "Among these genes, Mmp9 is specifically related to lung cancer." (PMID 27461468, 2016). "Next, we investigated whether the NF-κB/MMP9 axis is critical to the invasive capacity of lung cancer cells." (PMID 27127879, 2016). "MMP2 is a more sensitive predictor of lung cancer progression, metastasis, and survival than MMP9." (PMID 26388610, 2015). "In addition, Id1 induces snail1expression in kidney epithelial cells and positively regulates MMP-9 expression in breast and lung cancer cell lines." (PMID 24970809, 2014). "A recent study indicated that Twist increased MMP9 activity in lung cancer H358 cells." (PMID 23626784, 2013). "However, MMP-9 is still inconclusive, since there is only an extremely low level of MMP-9 detected in A549 human lung cancer cells." (PMID 23226337, 2012). "In addition to forming perfusable tumor nodules, the A549 cells grown in the ex vivo 3D lung model produced MMP-9 that is produced by lung cancer cells in patients." (PMID 23028922, 2012). "Thus, individuals with the MMP9 -1562 T/T genotype have shown a protective effect against the development of lung cancer compared to the reference genotype (-1562 C/C)." (PMID 22455335, 2012). "In this sense, the overexpression of MMP2, MMP9 and MMP3 has been detected in various types of human cancer, such oesophageal cancer, gastric carcinoma, ovarian and lung cancer, and has been significantly associated with tumour progression and decreased survival." (PMID 22455335, 2012). "Strikingly, these cultures also express elevated Mmp10 mRNA, but no increase in Mmp2, Mmp7, Mmp9, Mmp11, Mmp12 or Mmp14, other Mmp species commonly linked to lung cancer." (PMID 22545096, 2012). "Only two studies have evaluated the association between the MMP9 -1562 C/T polymorphism and lung cancer risk, both finding a non-statistically significant association." (PMID 22455335, 2012). "In addition, Skp2 overexpression induces the expression of matrix metalloproteinase (i.e. MMP-2, MMP-9) and invasion of lung cancer cells." (PMID 21386910, 2011). "Moreover, SAA1 and SAA2 seem to be also involved in lung cancer metastasis, by inducing the expression of matrix metallopeptidase-9 (MMP-9) by macrophages." (PMID 22229091, 2011). "Pleural fluid marker analysis revealed highly significant differences in the levels of seven of the analysed markers between benign and lung cancer patients: the concentrations of all seven markers, MMP-9, MMP-3, CycD1, Ki67, ImAnOx, carbonyls and p27, were lower in cancer patients by 9–65%." (PMID 20216542, 2010). "Therefore, it appears that FAK promotes A549 lung cancer cell invasion through the ERK/MMP9 pathway." (PMID 19568240, 2009).
lung carcinoma (continued). "Our data suggest that fibronectin-mediated activation of FAK that leads to lung cancer metastasis could occur through ERK or PI3K/Akt regulation of MMP9/calpain-2 or MMP9/RhoA activity, respectively." (PMID 19568240, 2009). "Similarly, MIA-690 counteracted IR-induced phosphorylation of STAT3 and NF-κB, which, in lung cancer, has been linked to the upregulation of COX-2, MMP9, and cyclin D1, factors that contribute to increased cancer cell survival, proliferation, invasion, and EMT." (PMID 40244089, 2025). "Previous studies have shown that simvastatin modulates the expression of MMP-2 and MMP-9 in lung cancer tissue, as well as in a human lung adenocarcinoma cell line, indicating that simvastatin may play a role in in the prevention and treatment of lung cancer." (PMID 36835197, 2023). "In addition, MMP-9 is involved in lung cancer invasion, metastasis, angiogenesis, and progression." (PMID 35745729, 2022). "Thus, rhein may be a potential drug and the Stat3/Snail/MMP2/MMP9 pathway may represent novel potential targets for the treatment of lung cancer." (PMID 35178453, 2022). "Here, we want to stress that, although we present in this work only data involving both breast and lung cancer, as the two cancers may be related, we found the presence of the 65 kDa MMP-9 also in prostate cancer, gastric cancer, and oropharyngeal cancer samples." (PMID 35723387, 2021). "Furthermore, Gene 33 expression exhibits an inverse relationship with the expression of metalloproteases MMP-2 and MMP-9 in lung cancer cells, suggesting that it may inhibit EGF-induced invasion." (PMID 34206547, 2021). "Interestingly, TGM2 suppression greatly reduced MMP9 expression in a lung cancer cell line suggesting that TGM2 may influence MMP9 expression also in skin." (PMID 32575800, 2020). "Therefore, targeting MMPs, especially MMP‐9, might blockade lung cancer metastasis and improve survival rate." (PMID 32180962, 2020). "Also, Mmp9 and Mki67 were overexpressed in both lung cancers." (PMID 31921388, 2019). "Finally, survival analysis of lung cancer patients using the kmplot.com software showed that a high expression of genes involved in ECM degradation, such as ADAM19 (p = 3.3E−5), ADAMTS6 (p = 0.00032), or MMP9 (p = 0.04), was associated with a poor prognosis." (PMID 30814494, 2019). "Loss of epithelial protein marker E-cadherin, the concurrent upregulation of mesenchymal protein markers vimentin, and the upregulation of MMP-9 play a dominant role in the metastatic process and could be regulated by E2 in various cancers, including breast, ovarian, colon, and lung cancer." (PMID 28717394, 2017). "In addition, increased MMP3 protein levels and MMP9 activities are noted in tumor tissues from obese lung cancer patients, which may also result from exosome-mediating protein transfer." (PMID 29137230, 2017). "Interestingly, level of IL-8 was found to be decreased by ~8.1 folds (cancer: 16.5 ± 1.3 pg/ml; HD: 134.4 ± 23.9 pg/ml; P < 0.0001) but MMP-9 level was found to be increased by ~1.6 folds (cancer: 1126.2 ± 112.4 ng/ml; HD: 703.6 ± 98.2 ng/ml; P < 0.05) in lung cancer patients compared to HD." (PMID 27811960, 2016). "Furthermore, inhibition of the NF-κB/MMP9 axis decreases lung carcinoma invasive potential." (PMID 27127879, 2016). "Therefore, the PAI-2 and MMP-9 IHC panel we identified from markers of PA and MMP families could be used to stratify lung cancer patients by risk and select patients for more aggressive treatment." (PMID 26230665, 2015). "In conclusion, the present study demonstrated that AD is able to inhibit the migration and invasion of lung cancer cells by suppressing the PMA-induced expression of MMP-9, the mechanisms of which may involve the suppression of IκB phosphorylation and the consequent NF-κB activation." (PMID 24137258, 2013). "Interestingly the gene expression levels of MMP-9 were decreased in lung cancer specimens." (PMID 22593690, 2012).
lung carcinoma (continued). "We examine TAM roles from pre-metastatic niche formation to tumor colonization, using breast and lung cancer brain metastases to illustrate how TAMs disrupt the BBB and facilitate immune evasion through molecules like ANGPTL4 (angiopoietin-like 4) and MMP9." (PMID 41727473, 2026). "Moreover, the changes in Occludin and E-cadherin were further examined by IF, pointing that circDENND4C might change the metastatic ability of lung cancer cells via targeting the miR-200b/MMP-9 axis, further acting on the proteins of cell adhesion and tight junction." (PMID 40034591, 2025). "In contrast, miR-145-5p silencing upregulated MMP-2 and MMP-9 mRNA and protein levels, suggesting a key function of miR-145-5p in lung cancer cells through the regulation of MMP-2 and MMP-9." (PMID 40149594, 2025). "SP DNA levels were assessed using droplet digital PCR, and MMP-9 and MMP-2 protein expression were evaluated by immunohistochemistry in 120 lung cancer samples." (PMID 40321254, 2025). "Using the Lung Cancer Explorer platform, we observed that MCM4 expression was positively correlated with MMP9 and MMP12 across both TCGA and GSE32863 datasets, supporting a potential role of MCM4 in promoting ECM degradation and invasion." (PMID 40564876, 2025). "The inhibitory effects of ACE2 on MMP-9 and HIF-1α in lung cancer align with results from several previous studies." (PMID 41303321, 2025). "Lung cancer induction dramatically activated c-MYC and MMP9 gene expression by about 161 and 64% compared to those of the negative control group." (PMID 39338293, 2024). "For instance, lung cancer cells secrete extracellular vesicles containing amphiregulin (AREG), which induces abnormal activation of the EGFR signaling in OCs, upregulating MMP-9 and thus triggering osteolytic metastasis." (PMID 38571500, 2024). "Since MMP9 and PRRG2 are key downstream targets of ZBTB11 and/or SET in regulating the metastasis of lung cancer cells, we also considered them in the clinical survival analyses." (PMID 38355937, 2024). "NNK administration stimulated inducible lung cancer biomarkers, including (i) ICAM-1 level, c-MYC, and MMP9 genes, (ii) inflammation, (iii) angiogenesis, and (iv) proliferation." (PMID 39338293, 2024). "Using a combination of in vitro and molecular docking analyses, we found that silymarin effectively reducing the lung cancer cells' motility and invasion by modulation of expression of MMP-2 and MMP-9." (PMID 39431222, 2024). "The primary objective of this study to investigate the impact of silymarin on the proliferation of lung cancer A549 cells, particularly by examining its impact on the expression and activity of MMP-2 and MMP-9." (PMID 39431222, 2024). "SET interacts and collaborates with ZBTB11 to promote lung cancer cell migration and invasion, primarily through SET-ZBTB11 complex-mediated transcriptional activation of matrix metalloproteinase-9 (MMP9)." (PMID 38355937, 2024). "To evaluate the anti-lung cancer effect, we estimated three anti-lung cancer biomarkers: Intercellular Adhesion Molecule-1(ICAM-1), MYC proto-oncogene, bHLH transcription factor(c-MYC), and Matrix metalloproteinase-9 (MMP9) genes." (PMID 39338293, 2024). "In lung cancer, which is responsible for the most cancer-related deaths worldwide, quercetin significantly reduced the protein expression of MMP-2 and MMP-9 and increased TIMP-2 expression." (PMID 39335164, 2024). "In SAL-treated human lung cancer cells (A549) and human bladder cancer cells (T24), a significant reduction in MMP-2 and MMP-9 activity was found." (PMID 37644107, 2023). "The comparison of lung cancer subtypes in the prevalence of MMP-2-735C/T and MMP-9-1562C/T genotypes complemented our research." (PMID 37445754, 2023). "MMP-9/TIMP-1 imbalance is a common mechanism of malignant tumor invasion and metastasis, and PI3K/AKT/NF-κB pathway plays a key role in the process of lung cancer metastasis." (PMID 36690987, 2023).